CD4 (CD4 molecule)
Diseases named in the same sentence as CD4 in open-access papers (continued):
Sharing a sentence is not in itself a finding about the gene and the disease.
infection (continued). "In the case of chronic influenza virus infection, antigen-specific CD8+ CTL activity is impaired by exhaustion, and CD4+ CTLs act instead of these cells to contribute to infection control." (PMID 33539379, 2021). "Flow cytometric analysis after polyclonal stimulation with anti-CD3/CD28 showed that the H1-DDA/TDB-induced accumulation of IL-17A-producing cells within the CD44+CD4+CD90+ population at week 2 post-infection was highly impaired in IL-23p19−/− mice." (PMID 34351501, 2021). "Further, we found that these EVs augmented viral trans-infection to CD4+ T-cells, triggered release of proinflammatory cytokines in HBMECs and altered monolayer integrity." (PMID 34530855, 2021). "This latter function reflects their ability to facilitate rapid recruitment of CD4+ T cells at the secondary site of infection and hence to enhance parasite elimination." (PMID 34557190, 2021). "The ΔPE_PGRS47 mutant has previously been demonstrated to display attenuated growth and enhanced CD4+ T cell responses in mouse infection models." (PMID 34346699, 2021). "We observed robust and increasing proportions of adaptive CD8+ and CD4+ T cell responses within the first 2 weeks of infection, despite the patients’ overall lymphphopenic state, illustrating the ability of these cell types to drive patient recovery." (PMID 33976217, 2021). "Tuberculosis infections were mirrored in these mice and demonstrate CD4 + T cell and macrophage-dependent granuloma-like structure formation after infection." (PMID 34090462, 2021). "The CD4 counts in PLWH in infection wave 2 were lower during active SARS-CoV-2 infection relative to wave 1 (median 172 versus 420 cells/μL, a decrease of 2.4-fold) and were below the 200 cells/μL clinically used threshold indicating a low CD4 count." (PMID 34608862, 2021). "During LCMV Cl 13 infection, IL-10-producing, virus-specific CD4+ T cells significantly increase in the spleen and the liver." (PMID 34696381, 2021). "Our data show that Envchronic viruses replicate mainly in the mucosal tissue, while Envacute viruses pass through the tissue with migratory cells and initiate infection in CD4+ T cell lines." (PMID 33177204, 2021). "Persons with recent infection, higher log viral load, higher CD4+ T cell count, higher education and using venues for sex had higher odds of clustering." (PMID 34762774, 2021). "As infection progressed, the accumulation of CD4+ CD44hi TET+ CXCR3+ T cells increased into the lung parenchyma and airways in Mtb-infected BCG-vaccinated mice that received Z-DC transfer." (PMID 34253059, 2021). "Adults living with HIV in the chronic phase of infection were included if they had at least three plasma viral loads and CD4+ T-cell counts spanning a year." (PMID 34793581, 2021). "Lastly, by day 26 post-infection this deconvolution model predicted a sizeable increase of the CD4+ T cell response, with a predicted 3 to 4-fold relative increase when compared to days 0 and 6 post-infection." (PMID 34525131, 2021). "T cell frequencies for a single epitope as high as between 100–200 per million CD4+ T cells were observed in some persons even months after infection." (PMID 34965282, 2021). "When CD4+ T cell count drops below 200 cells/mm3, PLWH are susceptible to infection, even with ART, and have an increased risk of mortality." (PMID 34239993, 2021). "In humans, cytotoxic CD4+ T cells reach high frequencies during the acute stage of the infection induced by vaccinia virus." (PMID 33430234, 2021). "Our data uncover a novel mechanism by which iron modulates CD4+ cell differentiation and functionality and hence impacts infection control with intracellular pathogens." (PMID 34108960, 2021). "In contrast, infection with an MPT70-overexpressing Mtb strain promoted highly differentiated KLRG1+CX3CR1+ CD4 T cells with limited lung-homing capacity." (PMID 33879592, 2021).
infection (continued). "Infection of thymic epithelial cells leads to release of cytokines, which results in alteration of the microenvironment and apoptosis of immature CD4+CD8+ DP lymphocytes." (PMID 34113341, 2021). "(A) The concentration of CD4 T cells in the blood in all participants in all infection waves and at all timepoints as a function of disease severity." (PMID 34608862, 2021). "We observed a higher central memory (>75%) CD4+ T cells in response to stimulation, both in the low dose and high dose infection." (PMID 34484203, 2021). "In a comparison of PJP− and PJP+ MDA5+ DM patients with similar characteristics and medication, a shorter disease duration prior to infection was noticed, as well as low CD4+ T cell counts in infected patients." (PMID 34481528, 2021). "Another lymphocyte that helps coordinate the immune response to fight infection is CD4+ T lymphocytes, by stimulating other immune cells, such as macrophages, B lymphocytes (B cells), and CD8+ T lymphocytes (CD8 cells)." (PMID 34680577, 2021). "CD4 T cell death occurs after cellular infection with HIV, or in bystander or incompletely infected cells due to activation of cellular defense programs, and is halted and, to some extent, reversed by antiretroviral therapy (ART), even sub-optimal therapy." (PMID 34608862, 2021). "Of all 93 pseudoviruses made with patient-derived envelope clones, 80.6% (n = 75) and 5.4% (n = 5) clones established infection exclusively on R5 and X4-expressing U87.CD4+ cells, respectively." (PMID 34305873, 2021). "We first investigated the permissiveness of CD4+ T cells to infection with CCR5-tropic HIV-1 BAL harboring a GFP reporter (BAL-GFP) under different stimulation conditions." (PMID 34899645, 2021). "Further when we performed models with interaction terms between each factor and study period, we found significant interactions only for CD4, viral load and mode of infection." (PMID 34362172, 2021). "To identify the tissue reservoir of infected human CD4+ T cells after i.p. infection in CD34 mice, we used RNAscope to visualize HIV-1 RNA in spleen and GALT (ileum and colon) sections." (PMID 33673566, 2021). "As expected, TN were refractory to direct cis infection of HIV-1BaL using either PHA/IL-2- or CCL-19-conditioned medium, while total CD4+ T cells were susceptible to productive cis infection." (PMID 33688006, 2021). "(F) The distribution of spike-specific CD4+ T cells into FlowSOM clusters differs between the infection-naïve and convalescent individuals after the second vaccine dose." (PMID 34636722, 2021). "Cytomegalovirus has a significant influence on the CD4+/CD8+ T cell ratio by increasing circulating CD8+ T cells in response to the infection." (PMID 33937149, 2021). "Once in the CNS, HIV can then infect glial cells (microglia and astrocytes) through direct infection mediated by CD4/chemokine fusion of HIV gp120 in the case of microglia or through endocytosis for astrocytes." (PMID 34451992, 2021). "If the number of replicates is decreased to a standard of 3 replicates per participant, a higher infection rate of 4.63% (p24+ in CD4 T cells cultured alone) is necessary." (PMID 34276657, 2021). "T cell memory in the blood contracts several months post-infection although responses were remarkably variable, likely in part reflecting HLA-restricted responses to specific epitopes as we illustrated across 7 CD4 T cell epitopes followed over time." (PMID 33608522, 2021). "IL-7 can also be increased in HIV-1 and SIVmac infection as a consequence of CD4+ T cell depletion, as shown during primary infection in the blood and intestine." (PMID 34220857, 2021). "Although we observed a comparable CD4 T cell response in the blood between the two infections, insufficient DC activation and reduced IFN-I production following ZIKVBR infection are associated with a poorly activated CD8 T cell response." (PMID 34193875, 2021).
infection (continued). "WLWH with lower CD4 counts were non-significantly more likely to have multiple hrHPV infections (ptrend = 0.13) and given multiple hrHPV infections, more likely to have multiple persistent hrHPV infection compared to women with higher CD4 counts." (PMID 33608036, 2021). "One of the most striking observations from this study, and the third and final question we set out to answer, was the remarkably distinct phenotypes of spike-specific CD4+ T cells from infection-naïve vs. convalescent individuals who were fully vaccinated." (PMID 34636722, 2021). "The significance of iATP measurement in CD4+ cells predicting acute rejection and infection is currently under investigation because different studies have found contradictory results." (PMID 33535640, 2021). "Work in murine models has shown that CD4 + T cells play an important role in protective immunity to erythrocytic stages of the infection." (PMID 34666102, 2021). "Specifically, skin resident CD4+ memory T cells (TRMs) responsible for controlling the secondary infection recruit iMOs to the challenge site." (PMID 34712235, 2021). "Whereas class-switched but not IgM+IgD+ MBCs appeared as important predictors of reduced risk of symptomatic infection, the presence of Treg cells along with TH1 and TH17 CD4+ T cell responses were features of protection from asymptomatic P. vivax malaria." (PMID 34128836, 2021). "As the infection enters the latency phase, CD4 T-cells become less inflammatory and begin to produce IL-10, which downregulates CD8 T-cell proliferation but not their effector function." (PMID 34603296, 2021). "In order to induce rapid progression to neuroAIDS, another model employs immune modulation by depletion of CD4+ T lymphocytes prior to SIVmac251 inoculation in rhesus macaques, resulting in productive infection in microglia." (PMID 34451482, 2021). "Phenotypic features of spike-specific CD4+ T cells differ between infection-naïve and convalescent individuals after vaccination." (PMID 34636722, 2021). "Immature precursors of CD4+ T cells can also be lost either by direct infection of thymic progenitor cells or by infection of cells that secrete cytokines needed for CD4+ T cells to mature." (PMID 34696319, 2021). "The acute infection course was consistent among animals as determined by both CD4 T cell frequency and virus replication kinetics." (PMID 34229275, 2021). "These expression levels aligned with decreased infection in differentiated myeloid cells versus high infection in CD4+ T cells." (PMID 33669846, 2021). "A recent study found comparable levels of SARS-CoV-2-specific central memory CD4+ T-cells one month after vaccination compared with those from patients that had recovered from a previous infection, which supports the results we present here." (PMID 34960185, 2021). "This was accompanied by fewer CD3+CD8+ and CD3+CD4+ cells in brainstems of Optn−/− animals during infection." (PMID 34518549, 2021). "A decrease in the bacillary load of ΔhisD, equivalent to the CD4 T-cell activated primary macrophages was observed 48 h post infection." (PMID 33767335, 2021). "To decipher between a CD4+ and CD8+ T-cell mediated phenotype, we performed an HIV-1 spreading infection assay on an isolated CD4+ T-cell population." (PMID 34122382, 2021). "We found that TH1 (CD4+ CD44+ FoxP3- Tbet+) cells were the predominant CD4 T-cell subset during UgCl233 infection, ranging from 20% - 48% of activated CD4 T-cells." (PMID 35186781, 2021). "HIV establishes a preferential infection and depletion of CD4+ T cells, increases T cell activation, exhaustion and death, impairs antigen presentation, CD4+ and CD8+ T cell functionality." (PMID 33746974, 2021). "Latent HIV‐1 DNA can be mainly found in viral reservoirs such as CD4+ T cells; however, myeloid cells (in particular microglia) can also contribute to persistence of the infection during ART." (PMID 34289240, 2021).
infection (continued). "Because macrophages express both the primary receptor CD4 and co-receptor CCR5, they are highly susceptible to productive infection by CCR5-tropic HIV strains." (PMID 34356516, 2021). "Nevertheless, it was unlikely that the delay differentiation before day 16 after infection accounted for the delayed accumulation of IFN-γ–producing CD4+ T cells in the lungs." (PMID 34554927, 2021). "We measured productive infection in vitro on day 10 using flow cytometry by staining for intracellular p24-Gag expression and surface CD4 downregulation (day 10)." (PMID 33441346, 2021). "For longer periods from infection or vaccination, when a lower frequency of circulating specific CD4+ T cells is expected, it is possible to increase the total amount of stimulated cells as well as of recorded cells." (PMID 34910301, 2021). "EVs derived from HIV-1 infected macrophages (Mɸs) and dendritic cells (DCs) can transfer infection to uninfected CD4+T-cells and induce robust viral replication." (PMID 34530855, 2021). "At the time of infection, macrophages and unstimulated CD4+ T cells harbor more defective proviruses compared to activated CD4+ T cells with up to 80% of the infected cells containing 5’ deletions or mutations." (PMID 34962974, 2021). "As the proinflammatory cytokine, IFN-γ and IL-2 were released largely to limit T. gondii during different infection phases; they are considered to be indicator for triggering of CD4+ Th1 and CD8+ cytotoxic T cells." (PMID 35003067, 2021). "Since a sizable percentage of people experiencing S. aureus SSTI has recurrent infections, it will be very informative to analyze the CD4+ Tsrm response to S. aureus in this population." (PMID 33796109, 2021). "Lymphocytes are responsible for the cellular and antibody responses to infection; for instance, the low number of CD4+ T lymphocytes in HIV infection are responsible for the susceptibility to infections." (PMID 34460817, 2021). "To establish T-bet’s protective role in host defense against intracellular pathogens, we implemented the well-established intraperitoneal (i.p.)model of infection with T. gondii that triggers and depends on a robust CD4+ TH1-derived IFN-γ response." (PMID 33465134, 2021). "Recently, 5-OP-RU vaccination of mice was not shown to be protective of TB infection and contributed to a delayed CD4 response to the infection." (PMID 33777010, 2021). "In the co-cultures with both CD4 and CD8 CAR T cells, the frequency of infection of CD4 CAR T cells was reduced by 49% (N = 4) compared to cultures lacking CD8 CAR T cells." (PMID 33752225, 2021). "Infection provoked by HIV-1 is marked by an accelerated reduction in CD4+ T cells, T cell dysfunction, thymic dysfunction, lymphoid destruction, and pan-cellular defects attributed to stem cell dysfunction." (PMID 34946138, 2021). "During infection, in patients with favorable outcomes, we observed a rise in the lymphocyte count, in the monocyte and in Treg lymphocyte counts, and in the CD4+ and in CD8+ T lymphocytes count but a reduction in the CD4+/CD8+ T lymphocyte ratio." (PMID 34439967, 2021). "Transcriptional silencing of HIV in CD4 T cells generates a reservoir of latently infected cells that can reseed infection after interruption of therapy." (PMID 33635929, 2021). "Quantitative analysis of HIV-1SF33-infected cells showed that hBD-2PTD and hBD-3PTD reduced the infection of CD4+ T lymphocytes, CD68+ macrophages, and CD1c+ DC by 20–70% compared with untreated tissues." (PMID 34696473, 2021). "Acquired CD4+ T cell mechanism are essential for the protection against colonization and subsequent development of infections by S. pneumoniae." (PMID 35822055, 2021). "In this study we investigated how the environmental context of culturing CD4+ T cells affects the expression of CCR5 and susceptibility to infection by HIV-1." (PMID 34899645, 2021).
infection (continued). "Acute (early) HIV infection is marked by infection of memory CD4+ T cells (which express CCR5) in mucosal lymphoid tissues and leads to death of many infected cells." (PMID 34696319, 2021). "During in vivo infections by L.a. parasites, a mix of different CD4 T cell responses is observed (Th1, Th2), in addition to the presence of other cell types such as NK cells and ILC2, which can produce IFN-γ or IL-4 for instance." (PMID 34557194, 2021). "Previous data has shown that the source of the infection-associated IFNγ is complex, involving NK, NKT, CD8+ and subsequently CD4+ T cells, cell populations that all decrease in size during T. b." (PMID 34200074, 2021). "In contrast, systemic administration of the same vaccine induced a population of tetramer+ CD4+ migratory T cells enriched within the pulmonary vasculature that migrated to the lung tissue upon challenge and efficiently protected mice against infection." (PMID 34113356, 2021). "Three immunotypes of patients with severe forms of infection have been identified: (i) with robust activation of CD4+ T cell, (ii) with an intense CD8+ T cells response and weaker CD4+ T and B cells, and (iii) low percentage of activated lymphocytes (20%)." (PMID 34946179, 2021). "After 60 days of infection, the nPVL correlated with the frequency of CD4+CD25+ T-cells (Pearson R = 0.977, p = 0.001) only in blood but not with CD4+Ki67+ T-cells." (PMID 34685494, 2021). "Within this cell type, CD4+ T cells produce a greater response than CD8+ T cells and have been associated with the control of primary infection." (PMID 34578848, 2021). "The IFN-γ and TNF-a response was delayed to week 3 post infection in Mtb-specific CD4+ and CD8+T cells in the high dose group." (PMID 34484203, 2021). "The clinical trial data of CD4-IgG2 revealed the possibility of continued development, even though the potential to enhance infection of some HIV-1 strains did limit its application." (PMID 33807292, 2021). "Upon infection of DCs with hMPV and coculture of these cells with CD4+ T cells, a significant decrease in the activation of the T cells was detected compared to control conditions." (PMID 33809875, 2021). "CD8+ memory T cells established a static, resident population in the epidermis at the original site of infection, while a dynamic population of CD4+ T cells trafficked through the dermis and re-entered the circulation." (PMID 33668777, 2021). "In contrast, LN, liver, and spleen of non-infected mice (green fluorescence) did contain huCD4+ cells, suggesting either that infection depletes these cells from solid tissue, or that CD4 is downregulated by Nef." (PMID 34717655, 2021). "In vivo infection, the body’s immune cells, such as CD4+T cells, neutrophils, NK cells, and macrophages interact with each other to coordinate an antifungal response." (PMID 34339354, 2021). "In the human rhinovirus challenge study yielding Dataset 1, MHC class II tetramers were used to identify rhinovirus-specific CD4+ T cells with the goal of tracking phenotypic changes over the course of infection." (PMID 34350827, 2021). "CD4 cells are the primary target of infection by HIV‐1 and resting ones are the best characterized latently infected cells that comprise the majority of the reservoir." (PMID 34797948, 2021). "CD8 T cells and other un-identified cells, possibly NKT or ILCs, were a minor source of IL-17 during primary or secondary infection with B. pertussis and the proportion of these was enhanced in anti-CD4 treated mice." (PMID 33976385, 2021). "CD4+ TRMs present in the skin after resolution of Leishmania Major infection are retained long after disease resolution, where they produce IFN-γ and enhance the recruitment of circulating memory cells to the site of Leishmania challenge." (PMID 34445713, 2021).